HOXA9 (homeobox A9)
Diseases named in the same sentence as HOXA9 in open-access papers (continued):
Sharing a sentence is not in itself a finding about the gene and the disease.
tumor (continued). "Interestingly, the list of the top 100 significant differentially methylated genes contained tumor-associated genes HNRNPH1 (top two), HOXA9 (top seven) and HIST1H2BM (top thirty-seven) among the top matched." (PMID 36358793, 2022). "Our IHC staining showed that HOXA9 is overexpressed in tumor tissue compared to normal epithelium." (PMID 35743243, 2022). "Modulating HOXA9 expression could either promote or inhibit tumor progression through different mechanism, depending on context." (PMID 36387262, 2022). "This prompts us that HOXA9 expression in tumors might have heterogeneity, and research on the role of HOXA9 in various tumors depends on the tumor itself." (PMID 36376832, 2022). "In the present study, HOXA9 expression was correlated with tumor EMT characteristics." (PMID 35783150, 2022). "Abnormal expression of HOXA9 in malignant tumors can regulate not only cell proliferation and apoptosis, cell differentiation, invasion and metastasis, and drug resistance, but also the proliferation and self-renewal of tumor stem cells." (PMID 35111226, 2022). "Thus, the tumor-suppressive effect of ST8SIA6-AS1 is mediated by the ST8SIA6-AS1/miR-5195-3p/HOXA9 axis." (PMID 35783150, 2022). "We found that HOXA9 had greater expression in the tumor tissue compared to normal colon." (PMID 35743243, 2022). "Comparatively, other Hox family members like HOXA9 may exhibit tumor suppressive roles by upregulating the expression of BRCA1 in breast cancer cells." (PMID 35846378, 2022). "Furthermore, the quantitative evaluation of gene promoter methylation through MethyLight assay was confirmed and validated by clonal bisulfite sequencing of selected tumor tissue and normal DNA samples for HOXA9, HIC1, and SOX1 gene." (PMID 34778370, 2021). "Moreover, IGF1 has been described as a growth-regulatory MLL-ENL/Hoxa9/Meis1 target and as a direct C/EBPβ target gene involved in autocrine stimulation of transformed murine monocytes and in neoplasia." (PMID 33144337, 2021). "Based on these findings, we conclude that miR-182-5p may affect the initiation and development of NSCLC by targeting HOXA9 to diminish the tumor-inhibitory effect of HOXA9 on NSCLC." (PMID 31906958, 2020). "Moreover, in recurrent and progressive tumor samples, Isl1 and Hoxa9 are displayed by a remarkably high level of methylation when compared to nonrecurrent tumor samples." (PMID 33402862, 2020). "However, when all of the results are evaluated, the oncogenic or tumor-suppressive role of Hoxa9 in gynecologic cancers is inconclusive." (PMID 33402862, 2020). "Moreover, a detailed DNA methylation analysis of all stages of human melanoma revealed that Hoxa9 DNA hypermethylation had a function in tumor development when compared to benign samples." (PMID 33402862, 2020). "Moreover, while Meis1, Meis2, and Pbx1 expressions are downregulated, Hoxa9 expression is upregulated during the tumor initiation and progression of PC." (PMID 33402862, 2020). "The overexpression of Hoxa9 clears the tumor suppressor effects of miR-638." (PMID 33402862, 2020). "Therefore, to develop a system to deliver the key inhibitory domain of HOXA9, we cloned three partial DNA fragments of HOXA9 and analyzed its role in the invasion process of tumor cells." (PMID 33238593, 2020). "Additionally, HOXA9-transfected tumor cells showed significantly increased soft-agar clonogenic ability and tumor sphere formation." (PMID 33288848, 2020). "Our study highlights a HOXA9-NF-κB axis regulates both the apoptosis and autophagy to promote tumor development in cSCC, which may suggest novel intervention targets for cSCC therapy." (PMID 31683603, 2019). "In particular, 54 pairs of tumor and surrounding tissues were selected from patients with early and advanced NSCLC to determine the promoter methylation status of possible genes associated with NSCLC (PCDHGB6, HOXA9, MGMT, miR-126, SOCS3, NORE1A)." (PMID 30917582, 2019).
tumor (continued). "Through these additional analyses, we can confirm that Hoxa9 upregulation is essential for the leukaemic phenotype of BcorΔE9-10KrasG12D tumours, and Hoxa7 and Hoxb5 may also be important." (PMID 30902969, 2019). "However, in cSCC, our findings clearly demonstrate that HOXA9 plays tumor-suppressive roles and negatively regulates the expression of HIF-1α and its downstream glycolytic genes." (PMID 29662084, 2018). "Then, both the mRNA and protein expression levels of HOXA9 were examined in these tumor samples." (PMID 29662084, 2018). "We confirmed HOXA9 promoter methylation status in both cell lines and patient tumor samples." (PMID 27598218, 2016). "However a positive correlation between HOXA9 induction and invasive growth in the Claudin-low breast cells apparently contradicts its reported tumor suppressive activity." (PMID 27409175, 2016). "Finally, we characterize a putative actionable epigenetic switch involving HOX-genes with strong correlations to tumor differentiation states and propose that a link exits between KDM6A mutations and HOXA9 gene expression patterns." (PMID 25810763, 2015). "In previous reports, HOXA9 and ZNF154 methylation has been associated with tumour recurrence, and ISL1 methylation with tumour progression in predominantly low/intermediate-grade tumours." (PMID 26332997, 2015). "Similarly, tumor-related signatures, like Cyclin D1, HOXA9, BMI1 and PDGF were enriched for the deregulated genes." (PMID 26113842, 2015). "Interestingly, the final tumor volume was significantly correlated with HOXA9 expression levels, further strengthening the relevance of HOXA9 on tumor growth kinetics in vivo." (PMID 25762636, 2015). "Indeed, the oncogenic and tumor suppressive activities of deregulated HOXA9 expression in different tissues highlight the importance of tissue context for the functioning of deregulated developmental genes in cancer." (PMID 24886209, 2014). "In addition, knockdown of P-cadherin in HOXA9+ SKOV3-Par cells significantly reduced the ability of these tumor cells to attach to mesothelial cells (P < 0.01) and to migrate (P < 0.001)." (PMID 25023983, 2014). "Expression of HOXA9 in SCC4 cells also resulted in increased expression of BRCA1, suggesting that, in addition to promoting growth, reduced expression of HOXA9 may contribute to tumor genome instability." (PMID 24886209, 2014). "Additionally, HOXA9 hypermethylation was more common in tumours from patients older than 60 years of age (15/21) than among those of younger age (11/30; P = 0.023)." (PMID 17623056, 2007). "Therefore, HOXA9 might have dual functions as an oncogene or tumor suppressor gene depending on tumor heterogeneity." (PMID 39462379, 2024). "HOXA9 heterogenic role in carcinogenesis might depend on tumor type." (PMID 39462379, 2024). "Furthermore, its role as a biomarker for prognosis, stage stratification, correlation with immune cells of the tumor microenvironment, interactions with cofactors, and drug-gene interactions was also determined, aiming to understand the potential role of HOXA9 in cancer progression." (PMID 38904676, 2024). "Therefore, parallel methylation of Hoxa9/Isl1 in HG-NMIBC could be used as a predicted value for tumor recurrence and progression." (PMID 33402862, 2020). "Our findings highlight the pro-apoptotic and anti-autophagic roles of HOXA9 in skin tissue, support our previous finding that HOXA9 acts as tumor suppressor in cSCC, and emphasize a newly identified HOXA9- NF-κB axis that may provide novel intervention targets for cSCC therapy." (PMID 31683603, 2019). "HOXA9 may act as a tumor suppressor or an oncogene, depending on the context of specific cancers." (PMID 29662084, 2018). "But whether HOXA9 contributed to the alteration of tumour microenvironments need further proved." (PMID 28780773, 2017).
tumor (continued). "Considering that stem cell properties have been linked with tumor malignancy, together with our microarray data implicating the HOXA9 transcriptome in typical hallmarks of cancer, we hypothesized that HOXA9 could play a role in tumor growth in vivo." (PMID 25762636, 2015). "A progressive increase in promoter-to-exonic methylation was noted in the paralogous HOXA9 and HOXD9 genes with increasing tumor stage." (PMID 40676709, 2025). "The sponging of particular miRNAs to the HOXA9 3’UTR not only contributes to increased proliferation, migration, invasion, and metastasis but also facilitates tumor recurrence." (PMID 38904676, 2024). "A recent animal study confirmed that ST8SIA6‐AS1 knockdown blocked the tumor growth of GTI‐1 cells in the nude mouse model with significantly reduced tumor volume and weight, which was possibly mediated via miR‐5195‐3p/HOXA9 axis." (PMID 37904679, 2023). "The analysis of TCGA database showed that HOXA9 was highly expressed in HNSCC, and its expression level was related to tumour grade and lymph node metastasis status." (PMID 34850551, 2022). "Aberrant expression of HOXA9 is not only presented in AML, but also observed in various solid tumors, making it an interesting and potential target in tumor therapy." (PMID 36376832, 2022). "It is further confirmed that there is a direct binding site between KCNQ1OT1 and HOXA9, and rescue experiments demonstrate that ALKBH5‐KCNQ1OT1‐HOXA9 axis affects tumour proliferation, invasion and metastasis." (PMID 34850551, 2022). "The transcript levels of HOXB1, HOXA7, HOXB5, HOXD8, HOXB9, HOXA9, and HOXA11 were significantly lower in ccRCC tumor tissues compared to adjacent normal tissues, which was consistent in both TCGA and ICGC cohorts." (PMID 36387262, 2022). "HOXA9 and MEIS1 homeobox oncogenes (adjacent and coexpressed with miR-196b), along with FAS tumor suppressor, are direct targets of miR-196b and drive carcinogenesis in KMT2A-r cases in a bidirectional manner." (PMID 36010971, 2022). "We found not only that both HOXA9 and ALDH showed increased expression in tumor cells, but also that they were co-expressed in cells in both tissue samples." (PMID 35743243, 2022). "ZEB1 expression was downregulated in AML patients, and Zeb1 KO in the malignant counterparts of HSCs — leukemic stem cells (LSCs) — accelerated MLL-AF9– and Meis1a/Hoxa9-driven AML progression, implicating Zeb1 as a tumor suppressor in AML LSCs." (PMID 33108352, 2021). "miR-641 has been reported to be a tumor-suppressive miRNA by targeting various downstream genes, including ZEB1, HOXA9, MDM2, and YAP1." (PMID 34603448, 2021). "The promoter methylation levels of selected candidate genes (RASSF1A, DAPK1, SOX1, HOXA9, HIC1, SPARC, and SFRP1) were quantitatively evaluated by MethyLight in tumor DNA samples of patients with EOC." (PMID 34778370, 2021). "Induction of Zeb1 KO in LSC mouse models of MLL-AF9– and Meis1a/Hoxa9-driven AML accelerated disease progression, implying that Zeb1 acts as a tumor suppressor in AML LSCs." (PMID 33108352, 2021). "In the late-tumor growth stage, BMPER, CXCL10, and HOXA9 were all lowly expressed, while CD34 was highly expressed." (PMID 32432046, 2020). "On day 20 of tumor growth, BMPER was highly expressed, while CXCL10, HOXA9 and the tumor blood vessel marker CD34 were lowly expressed." (PMID 32432046, 2020). "Among these upregulated DEGs, PNCK, HOXA9, and HOXB8 were all reported to be related to tumor progression in several cancers." (PMID 33318296, 2020). "Along with further tumor progression, BMPER expression was gradually reduced, while CXCL10 and HOXA9 expression was gradually elevated, which was spatially associated with CD34 expression." (PMID 32432046, 2020). "In our study, tumor growth curves of xenografts were analyzed to confirm that in the early stages of tumorigenesis, BMPER was highly expressed, while CXCL10, HOXA9, and CD34 were lowly expressed." (PMID 32432046, 2020).
tumor (continued). "Analysis of mut-KRAS needs to be tumor-informed or performed with NGS, whereas meth-HOXA9 can be analyzed directly in a simple, fast, and cheap ddPCR assay." (PMID 33322500, 2020). "The results further confirmed that the hypermethylation of HOXA9 and the hypomethylation of KRTAP8-1, CCND1, and TULP2 were observed in LUAD tumor samples." (PMID 31850197, 2019). "In our previous study, Homeobox A9 (HOXA9) was significantly downregulated and identified as tumor suppressor in cSCC tumors and cells." (PMID 31683603, 2019). "In this study, we systematically analyzed the DNA methylation data of LUAD and found that the hypermethylation of HOXA9 and the hypomethylation of KRTAP8-1, CCND1, and TULP2 were observed in LUAD tumor samples." (PMID 31850197, 2019). "Another methylation panel of six genes (SOX17, HOXA9, AJAP1, PTGDR, UNCX, MARCH11) was evaluated in tumor and adjacent normal lung tissue from 90 NSCLC patients showing a high sensitivity (96.7%) and specificity (60%)." (PMID 30917582, 2019). "Overexpression of HOXA9 was found to enhance ALP activity and mineralization, as well as in vitro tumour cell migration and invasion, whereas downregulation of this marker inhibited these processes." (PMID 31043660, 2019). "In these LUAD patients, the methylation of HOXA9 was significantly upregulated, whereas the methylation of KRTAP8-1, CCND1, and TULP2 were downregulated obviously in tumor samples compared with adjacent tissues." (PMID 31850197, 2019). "Our work provides evidences to demonstrate the direct binding of HOXA9 on RELA promoter and deepen the understanding of HOXA-RELA regulator axis, which highlights the tumor-suppressive role of HOXA9 in cSCC." (PMID 31683603, 2019). "Both high HOXA9 and OXR1 promoter methylation levels discriminated normal from tumour samples with good sensitivity and high specificity (73 and 89% for HOXA9 and 87 and 100% for OXR1, respectively)." (PMID 28662726, 2017). "Down-regulated expression was observed for the tumor suppressor and inhibitor of WNT signaling CXXC4, and the differentiation inducing transcription factors, HOXA7 and HOXA9." (PMID 29100312, 2017). "HOXA9 was upregulated in CRC samples and positively correlated with tumor cell invasion and metastasis." (PMID 28969042, 2017). "We then identified the expression level of HOXA9 in CRC tissues and adjacent non-tumor mucosal tissues." (PMID 28969042, 2017). "We also studied the function of the HOXA9 itself in CRC and proved that the knockdown of this target led to significant repression of tumor cell proliferation and migration." (PMID 28969042, 2017). "Multiple tumor suppressors were expressed at lower levels in EBVaGCs including five (TFF2, RBP4, HOXA9, LRRN1, and RAP1GAP) that are known to be hypermethylated in cancers." (PMID 23671415, 2013). "For example, TXNIP (thioredoxin-interacting protein), EGR1, CBX7, HOXA9 and FOXN3 (checkpoint repressor 1) have tumor suppressor functions and are targeted by the potentially oncogenic miRNA miR-93, miR-183, miR-181b, miR-182 and miR-7." (PMID 21375733, 2011). "To explore the relationship between promoter methylation and gene expression in primary tumours we performed a qRT-PCR analysis of SOX9, HOXA9, AHR, ROBO1, and NR2F2 in a series of 36 MCL." (PMID 21603610, 2011). "The subsequent analysis in primary MCL identified five genes (SOX9, HOXA9, AHR, NR2F2, and ROBO1) frequently methylated in these tumours." (PMID 21603610, 2011). "In the present study, we find high methylation frequencies of HOXA9 and RASSF1A in tumours from this patient group." (PMID 17623056, 2007). "Additionally, HOXA9 hypermethylation was more prevalent in patients with stage II and III tumors when compared to stage I, suggesting its potential role in tumor progression and aggressiveness." (PMID 40699796, 2025).
tumor (continued). "The HOXA9 transcription factor serves as a molecular orchestrator in cancer stemness, epithelial-mesenchymal transition (EMT), metastasis, and generation of the tumor microenvironment in hematological and solid malignancies." (PMID 38062297, 2023). "Our IF co-staining for HOXA9 and ALDH also revealed that: (i) HOXA9- and ALDH-co-stained cells were present within the same regions of the tumor; (ii) both HOXA9 and ALDH showed increased expression in tumor tissue compared to normal tissue." (PMID 35743243, 2022). "Recently, there have been two manuscripts delineating the role for ZEB1 in HSCs and their differentiation using models with Zeb1−/−, where there was an acceleration of MLL-AF9 and Meis1a/Hoxa9-driven AML progression, implicating Zeb1 as a tumor suppressor in AML LSCs." (PMID 34639154, 2021). "Hoxa9 hypermethylation was also reported in the promoter methylation analysis of OSCC patient tissues and salivary rinses, which leads to the growth advantage of the tumor, and an increase in metastasis." (PMID 33402862, 2020). "Additionally, changes in tumor growth and progression after inhibiting BMPER, CXCL10, and HOXA9 expression in the xenografts should also be studied." (PMID 32432046, 2020). "In addition, DLBCL cell lines that overexpress HOXA9 and NANOG enhance tumor formation in a mouse model and enhance clonogenic ability in soft agar." (PMID 33288848, 2020). "Given that there was no overlap in the levels of meth-HOXA9 between the non-malignant tissue samples and the tumor tissue samples, however, we believe that the sample size for this purpose is reasonable." (PMID 33322500, 2020). "Furthermore, by establishing the tumor-bearing mice models, we proved that knock-down of circRNA CDR1as aggravated the inhibiting effects of DDP on tumorigenesis by targeting miR-641/HOXA9 axis in vivo." (PMID 32655321, 2020). "This in turn increases the stiffness of the tumor microenvironment as compared to the surrounding tissue, which then further enhances cancer progression via reducing levels of tumor suppressors PTEN and HOXA9 in cancer cells." (PMID 30670739, 2019). "HOXA9 belonging to HOX gene family is primarily identified to regulate embryonic development, maintain hematopoietic stem cells and play roles either as an oncogene or as a tumor suppressor in various tumors." (PMID 31683603, 2019). "Among the routine in vivo and in vitro evaluations of HOXA9 functions, when using xenograft tumor model, there is an inflection in tumor growth after around 9 days in the absence of HOXA9." (PMID 29662084, 2018). "Several studies suggest that HOXA9 and SOX17 are involved in tumor progression." (PMID 29270240, 2017). "Mean methylation levels within ISL1 and HOXA9 were significantly higher in recurrence and progression tumours compared to their no-recurrence counterparts (43.3% vs. 20.9%, p = 0.016 and 34.5% vs. 17.6%, p = 0.017, respectively)." (PMID 26332997, 2015). "The differential methylation frequency in HOXA9 and ISL1 may relate to several confounders, including the method in this study employed to define tumour methylation, and the relatively few low/intermediate-grade tumours for analyses." (PMID 26332997, 2015). "ISL1 and HOXA9 showed significantly higher mean methylation in recurrent and progressive tumours compared to non-recurrent tumours (43.3% vs. 20.9%, p = 0.016 and 34.5% vs 17.6%, p = 0.017, respectively)." (PMID 26332997, 2015). "In this study, we identified that HOXA9 promotes the assembly of floating EOC cells into multi-cellular aggregates and inhibits anoikis, and also stimulates tumor-peritoneum interactions and tumor cell migration." (PMID 25023983, 2014). "With the exception of HOXB5, higher promoter methylation frequencies were found among tumours from patients with relatively early FIGO stages (I-II) than late stages, but reached statistical significance only for HOXA9 and SCGB3A1 (P = 0.002, P = 0.020, respectively)." (PMID 17623056, 2007).